EEF2 (eukaryotic translation elongation factor 2)
Diseases named in the same sentence as EEF2 in open-access papers (continued):
Sharing a sentence is not in itself a finding about the gene and the disease.
cancer (continued). "EEF2 is an essential factor for protein synthesis that has been found overexpressed in numerous types of cancers and that plays an oncogenic role in tumor progression." (PMID 36038612, 2022). "When cancer cells are exposed to rapamycin, there is a robust elevation of p-eEF2 at Thr 56, indicating the activation of eEF-2K." (PMID 33144562, 2020). "Consistently, our recent study indicated that methylation of CDS of Snail, which recruited the YTHDF1 and eEF-2, can trigger its translation elongation and cancer metastasis." (PMID 32444598, 2020). "EEF2 has been found to be overexpressed in a wide variety of cancers as an antigen that can elicit both humoral and cellular immune responses." (PMID 32392242, 2020). "EEF2 is overexpressed in numerous cancer types and EFTUD2 knockdown induces apoptosis in breast cancer cells." (PMID 31575041, 2019). "For instance, the eukaryotic elongation factor 2 (eEF2), a key regulator of protein synthesis, was correlated with the progression of several types of cancer." (PMID 30916466, 2019). "Higher expression of EEF1A2, EEF1B2, EEF1G, EEF1D, EEF1E1 and EEF2 was observed in most of the cancer types, whereas reverse trend was observed for EEF1A1." (PMID 29342219, 2018). "Earlier studies have hinted at the pro-tumorigenic role of EEF1B2 and EEF2 in cancers which was evident in the present study also." (PMID 29342219, 2018). "This is notable because EEF2 is highly expressed in numerous cancers, where it promotes cell proliferation and EMT." (PMID 29282095, 2017). "As shown in the present study, knockdown of eEF2 by shRNA significantly inhibited cancer cell growth." (PMID 24589652, 2014). "Taken together, eEF2 protein is highly immunogenic and a promising target molecule for cancer immunotherapy." (PMID 24589652, 2014). "Compared to these TAAs, eEF2 is more attractive as a target molecule of cancer immunotherapy because of its high frequency of over expression in various types of cancers." (PMID 24589652, 2014). "We found that patients diagnosed with adenomatous polyps and carcinoma showed an increase in the phospho-Thr56 eEF2 aAb titer (P = 0,0015) when compared with patients identified as negative following colonoscopy." (PMID 24130777, 2013). "Accordingly, EEF2 phosphorylation appears to be mediated through multiple pathways thus alarming the need of combinatory inhibition of EEF2 kinase in anti-cancer therapy." (PMID 23443080, 2012). "Elongation factor E2 (EEF2), for example, was found to be upregulated in both mouse models, and its tumorigenic potential in gastrointestinal and breast cancers is well known." (PMID 20824133, 2010). "In addition to the regulatory role of eEF2K, our analysis revealed significant alterations in the total protein expression and phosphorylation of eEF2 across several cancer types." (PMID 39592671, 2024). "This underscores the clinical relevance of eEF2 as a therapeutic target in cancer." (PMID 39707196, 2024). "Indeed, it was recently found that (apparently) constitutive 7BS MTase mediated methylations on rRNA and the translation factors eEF1A and eEF2 promote tumor formation and cancer cell growth." (PMID 39351878, 2024). "In addition, eEF2 has also been found to overexpress in multiple other cancers, including lung, breast, prostate, glioblastoma, and hepatocellular cancer." (PMID 39409166, 2024). "The phosphorylation of eEF2 has been observed to be dysregulated in various cancers, where the phosphorylated status of eEF2 represents an inactive form that hinders its binding to ribosomes and affecting translation and poly(U)-directed polyphenylalanine synthesis." (PMID 39707196, 2024). "Therefore, elucidating the role of eEF2 and discovering its inhibitors in cancer is poised to greatly benefit the clinical outcomes of patients with cancer in the future." (PMID 39707196, 2024). "Therefore, it is imperative to uncover the functions of other phosphorylation sites of eEF2 in cancers." (PMID 39707196, 2024).
cancer (continued). "However, further research is necessary to assess how DDD107498 interacts with eEF2 and its inhibitory effects on cancer." (PMID 39707196, 2024). "Targeting eEF2 phosphorylation directly, particularly at T56, T57, or T59, could be a promising therapeutic strategy, potentially impairing cancer cell survival and inhibiting tumor progression." (PMID 39592671, 2024). "Furthermore, we raised valuable insight into the current understanding of eEF2 while emphasizing its potential as a target for developing novel therapies against cancer." (PMID 39707196, 2024). "Developing small molecules to specifically bind and inhibit the GTP-binding pocket of eEF2 could directly block translation elongation, thus inhibiting cancer cell growth." (PMID 39707196, 2024). "In HONE-1, NUGC-3 and HepG2 carcinoma cells, tylophorine, which is extracted from Tylophora indica, has been reported to increase the dephosphorylated protein level of eEF2, thereby accumulating the protein level of c-jun and cyclin A, thus arresting the cell cycle at G1 phase." (PMID 39707196, 2024). "Modulation of eEF2 and its kinases is therefore a potential drug target for cancer therapy." (PMID 37740172, 2023). "However, there are few reports that have actively investigated eEF2 inhibitors in the context of cancer; therefore, we attempted to discover a natural compound inhibitor of eEF2." (PMID 37088855, 2023). "Additionally, although eEF2 was reported as highly expressed in various cancer tissues, the implications of its increased abundance have not been investigated." (PMID 37088855, 2023). "In the present study, we find that eEF2 plays a positive role during the ESCC cancer process." (PMID 37088855, 2023). "In addition, CQ or BECN1-knockdown increased phosphorylation of eEF2 specifically under treatment of TGF-β1 not only in A549 but also in other types of cancer cells although this eEF2 phosphorylation at T56 varied among these cancer cells." (PMID 36230768, 2022). "Fluorizoline induces intracellular Ca2+ levels to rise swiftly and markedly that induces endoplasmic reticulum stress, and then promotes the phosphorylation of both initiation factor 2 (eIF2) and elongation factor 2 (eEF2), inhibiting protein synthesis and therefore inducing cancer cell death." (PMID 36348375, 2022). "In addition, EEF2 gene products have immunogenicity and are expected to be target molecules for a variety of cancer immunotherapies." (PMID 34437425, 2021). "This presents the possibility of directly targeting either RPL24 or eEF2 for anti-cancer benefit." (PMID 34895463, 2021). "In addition, the eEF2K/eEF2 pathway has been shown to control stress-induced autophagy and apoptosis in cancer cells." (PMID 32059483, 2020). "On the contrary, NH125 was found to increase eEF2 phosphorylation in cancer cells, thereby reducing protein synthesis levels which, in turn, could account for the anticancer activity of this compound." (PMID 29874821, 2018). "Indeed, NH125 was demonstrated to inhibit the activity of eEF2 kinase in vitro and to inhibit the growth of cancer cells with markedly increased expression of eEF2." (PMID 29874821, 2018). "In addition to EEF1A2, other translation factors EEF1B2, EEF1G, EEF1D, EEF1E1, and EEF2 were also found to be frequently overexpressed in different cancers." (PMID 29342219, 2018). "In this study, we propose a novel modification to PE by incorporating the NLS sequence at its C-terminus, to make it a selective agent against fast-proliferating cancer cells, as a nucleus-accumulated toxin should be separated from its natural substrate (eEF2) in slowly dividing cells." (PMID 27834892, 2016). "In conclusion, eEF2 that is overexpressed in a wide variety of cancers is a promising cancer antigen that can elicit both humoral and cellular immune responses and shows promise as a target molecule of cancer immunotherapy." (PMID 24589652, 2014).
cancer (continued). "Moreover, the eEF2 gene product is immunogenic and a promising target molecule of cancer immunotherapy for several types of cancers." (PMID 24589652, 2014). "Knockdown of eEF2 by shRNA significantly inhibited growth of cancer cells." (PMID 24589652, 2014). "Importantly, however, the specificity of phospho-Thr56 eEF2 aAb as cancer biomarker will have to be addressed." (PMID 24130777, 2013). "In patients with adenomatous polyps, the K-means clustering of individuals with a high seric titer of anti-Thr56 eEF2 antibody could be related to a higher potential of cancer progression." (PMID 24130777, 2013). "In addition, stronger induction of EEF2 phosphorylation mediated by AMPK activators and mTOR inhibitor was linked to more effective cancer cell growth inhibition." (PMID 23443080, 2012). "Additionally, inhibiting eEF2’s GTPase activity of could be a potential therapeutic strategy for patients with highly expressed eEF2 in cancer." (PMID 39707196, 2024). "Notably, recent findings suggest that the phosphorylation status of eEF2 differs between in vivo and in vitro cancer cells exposed to compound treatments; thus, elucidating the underlying mechanisms and identifying sensitive inhibitors is crucial for advancing both basic and clinical research." (PMID 39707196, 2024). "In addition, eEF2 was also related to chemoresistance in malignant tumors." (PMID 37740172, 2023). "It is suggested that EEF2 may be a promising target molecule for targeted cancer therapy." (PMID 34229299, 2021). "Likewise, translation initiation (EIF1A, EIF4A, EIF4G) and elongation (EEF1B2, EEF2) factors are well-known to play a role in cancer, as well as ribosome biogenesis related factors, like the pseudouridine synthase dyskerin and the 2′-O-methyltransferase fibrillarin." (PMID 32046192, 2020). "Although the elongation factors eEF1A and eEF2 are also involved in the abnormal translation program of cancer cells, there are very limited data on whether dissociation of the eEF1H complex is possible during the human cancer progression." (PMID 25472873, 2014). "No mutation was found in the eEF2 gene in the 10 cancers examined (data not shown)." (PMID 24589652, 2014). "However, the role for eEF2 in the tumori-genesis remains largely unknown and it is undetermined whether eEF2 can be a target molecule of molecule-targeted cancer therapy." (PMID 24589652, 2014). "However, phosphorylation of EEF2 by EEF2 kinase inactivates this factor which indicates that EEF2 kinase could be promising anti-cancer target." (PMID 23443080, 2012). "Interestingly, using pharmacological inhibition of EEF2 kinase demonstrated that anti-cancer activity of widely accepted inhibitor and anti-proliferation agent against different cancer cells was more correlated with induction of EEF2 phosphorylation than inhibition of EEF2 kinase activity." (PMID 23443080, 2012). "High mobility group box 2 (HMGB2) mRNA is ac4C‐modified by NAT10, and binding of eukaryotic translation elongation factor 2 (EEF2) to NAT10 increases HMGB2 expression and promotes cancer proliferation." (PMID 40448344, 2025). "Moreover, screening inhibitors on the basis of protein crystal structure has emerged as an effective strategy for cancer-targeting therapy research in recent years, thus targeting different domains of eEF2 to screen inhibitors could be a novel approach to impede cancer growth." (PMID 39707196, 2024). "In conclusion, six core genes including COL3A1, EEF2, FN1, PTPRF SDC2, and RAC1, and several cancer-related metabolic processes, signaling pathways, and overall survival rate of patients were identified in BM PCa." (PMID 34229299, 2021). "Eukaryotic extension factor 2 (EEF2) plays important roles in the GTP-dependent translocation of ribosomes along mRNA and proliferation, migration and survival of various cancers." (PMID 34437425, 2021).
cancer (continued). "Among them, candidate proteins EEF2, U2AF2 and FLNC are significantly enriched in the three pathways of “spliceosome” (p-value: 1.01 × 10−3), “proteoglycans in cancer” (p-value: 8.58 × 10−2) and “focal adhesion” (p-value: 1.48 × 10−3)." (PMID 34437425, 2021). "The gene with the lowest ES (ES = −1.2545) was eukaryotic translation elongation factor 2 (EEF2), a biomarker protein of some types of cancer that plays an important role in protein synthesis." (PMID 25466291, 2014). "Therefore, it is important to know whether or not loss of eEF2 expression affects tumor growth in consideration of the potential of eEF2 as a target molecule for cancer immmunotherapy." (PMID 24589652, 2014). "A dedicated immunoassay was developed and enabled us to validate phospho-eEF2 as a bona fide hypoxia-induced TAA and corresponding aAb as potential cancer biomarkers in mice and humans." (PMID 24130777, 2013). "Additionally, methylation of eEF2 catalyzed by FAM86A, enhances eEF2’s interaction with the ribosome, promoting protein synthesis and cancer cell proliferation." (PMID 39707196, 2024). "Despite evidence showing that inhibiting eEF2’s GTPase activity can suppress protein translation, targeted inhibition of eEF2’s GTPase activity in cancer has not been given due attention in previous studies." (PMID 39707196, 2024). "Indeed, it was demonstrated that both eEF2-KMT and the eEF1A MTase METTL13 were required for efficient growth of Ras-driven cancer, and that METTL13 depletion rendered the cancer cells hypersensitive towards other cancer drugs." (PMID 39351878, 2024). "Finally, they concluded that tylophorine arrested the carcinoma cell cycle through PI3K, PDK1, PP2A, eEF2, and c-jun signaling pathway." (PMID 39707196, 2024). "In a cancer cell line, A-484954 does not alter total eEF2 protein level but inhibits eEF2 phosphorylation." (PMID 36770760, 2023). "Keeping these lacunae in hindsight, we have undertaken a pan-cancer approach for comprehensive analysis of expression levels of seven elongation factors namely, EEF1A1, EEF1A2, EEF1B2, EEF1G, EEF1D, EEF1E1 and EEF2, using publicly available databases (Oncomine and TCGA)." (PMID 29342219, 2018). "Moreover, despite being highly expressed in various cancers, the posttranslational modifications of eEF2 have not been thoroughly studied." (PMID 39707196, 2024). "Inhibition of eEF2 is toxic to mammalian cells due to inhibition of translation, but here, we demonstrate that inhibition of LSG1, and possibly EFL1 by extension, may provide an effective prosenescent cancer therapy with lesser side effects since translation remains unimpaired." (PMID 31148378, 2019).
tumor (60 papers, 2005 to 2026). "Inhibition of eEF2 leads to slowing down of protein translation, and prevents tumor cells from growing under nutritional deficiency." (PMID 35127825, 2021). "The data can be supported by the report that high expression of eEF2, regulating the rate of peptide chain elongation during protein translation, was significantly associated with node positivity and tumor size in breast cancers." (PMID 31138781, 2019). "Only eEF2 expression showed a significant association with tumor size (mean expression in T1: 1.89 arbitrary units vs. mean of T2 to 4 tumors: 2.11, P = 0.016)." (PMID 23102376, 2012). "Other elements of EIF3 complex as well as translational machinery such as EIF3B, EIF3C, EIF4A, EEF1A, and EEF2 were already revealed as components of tumor-associated exosomes, which implicates exosomal delivery of translational machinery including EIF3A can be involved in tumor propagation." (PMID 31363116, 2019). "Proteomic profiling of MSC-exosomes identified key proteins, including ANXA1, ANXA2, EEF2, LGALS1, and PKM2, associated with tumor regeneration and chemotherapy response." (PMID 41683993, 2026). "Western blot analysis confirmed that ES treatment elevated the levels of Histone H4, Hspa8, MSN, Eef2, Aldoa, and Eno1, which is consistent with previous studies demonstrating Eno1’s tumor-suppressive function." (PMID 39940798, 2025). "Emerging evidence indicates that dysregulated mRNA elongation, involving alterations in eEF2 activity and eIF5A expression, also contributes to tumour cell growth." (PMID 41390489, 2025). "For example, EEF2 was upregulated in tumour samples (Log2FC = 1.356) but predicted favourable prognosis (hazard ratio (HR) = 0.451)." (PMID 38303549, 2024). "To evaluate the clinical significance of eEF2 in ESCC, we measured the correlation of eEF2 protein expression levels with tumor pathological grading, stage, and prognosis." (PMID 37088855, 2023). "IHC staining results indicated that Ki67 protein levels were reduced in tumors after eEF2 knockdown, indicating a significant reduction in tumor proliferation." (PMID 37088855, 2023). "Whole-genome proteomics predicted enolase 1 (Eno1), Hsp90ab1, Eef2, and vinculin as extracellular tumor suppressors." (PMID 35547745, 2022). "It was unexpected that the proteins such as Hsp90ab1, Eno1, Eef2, and vinculin were enriched in the secretome since they are considered tumor promoters intracellularly 35-38." (PMID 35547745, 2022). "These newly identified tumor suppressors, such as extracellular Eno1, Hsp90ab1, Eef2, and vinculin, downregulated Kdm3a, a histone demethylase, as well as the downstream oncogenic genes 21-24." (PMID 35547745, 2022). "EEF2K is well known as a regulator of protein synthesis through inactivating EEF2 to control tumour initiation and growth." (PMID 35184394, 2022). "Inhibiting eEF2K decreases the invasion and migration of tumor cells, while deletion of eEF2 or eEF2K overexpression promotes wound healing and invasion." (PMID 35127825, 2021). "Hypo-phosphorylated eEF2 then ensures rapid protein synthesis enabling tumour proliferation in vivo." (PMID 34895463, 2021). "Report indicated that significantly higher incidence of tumor recurrence and worse prognosis were found in elevated EEF2 patients, whereas silencing of eEF2 expression increased mitochondrial elongation and cellular autophagy." (PMID 34229299, 2021). "These are examples to show that if the mutant peptides derived from MAPK14 or eEF2 are used as neoantigen targets to stimulate the body, the specific immune response will likely benefit the destruction of tumor cells." (PMID 32241270, 2020). "Examination of TCGA dataset revealed overexpression of all the translation elongation factors being studied, except EEF1A1 which was downregulated and EEF2, which didn’t show any significant difference in expression between the tumor and normal groups." (PMID 29342219, 2018).